CD68 (CD68 molecule)
Diseases named in the same sentence as CD68 in open-access papers (continued):
Sharing a sentence is not in itself a finding about the gene and the disease.
psoriasis (17 papers, 2014 to 2025). An autoimmune condition characterized by red, well-delineated plaques with silvery scales that are usually on the extensor surfaces and scalp. "To determine whether the products of the genes are enriched in the macrophage subsets in murine psoriasis lesions, we performed immunohistochemical (IHC) analyses of skin biopsies and detected the products of macrophage-associated genes Cd68 and Ly6g enriched in the macrophages." (PMID 32929361, 2020). "When staining the skin lesions of psoriasis patients, it can be observed that CD68+iNOS+M1 increase and CD68+CD163+M2 decrease." (PMID 39148738, 2024). "Serial immunostaining and co-immunofluorescence of human psoriasis lesions further revealed a population of CD68+ cells (monocytes/macrophages) positive for GzmK." (PMID 38903528, 2024). "Immunofluorescence staining revealed that CD68+iNOS+ M1 macrophages were increased and CD68+CD163+ M2 macrophages were decreased in human psoriasis lesional skin compared with skin samples from normal individuals." (PMID 35837394, 2022). "In this study, we found that the expression of M1 markers (CD68 and iNOS) was enhanced in psoriasis mice and the pro‐inflammatory cytokines levels (TNF‐α, IL‐6, IL‐12, and IL‐23) were increased." (PMID 36444619, 2022). "For example, studies have found that the number of CD68+ M1-Mø is significantly elevated in psoriasis skin, indicating that infiltration of M1-Mø plays an essential role in psoriasis." (PMID 36467042, 2022). "The previous study demonstrated that macrophage marker CD68 was increased in psoriasis compared to normal skin, and coexpressed with CD163." (PMID 32411188, 2020). "The numbers of phosphorylated IκBα activated CD68+ Mφs were reduced in psoriasis plaques after treatment with new biomaterials based on nanoparticles significantly." (PMID 32411188, 2020). "Generally, CD163+ cell quantities in psoriasis-affected skin significantly dominated over CD68+ before and after all treatment regiments." (PMID 32411188, 2020). "T lymphocytes and macrophages are inflammatory cells involved in psoriasis tissue and can be detected via CD68." (PMID 30718736, 2019). "DLE lesional skin contained an increased abundance of CD3+, CD8+, and CD68+ cells at the DEJ, and CD20+ and CD68+ cells in the periadnexal area versus psoriasis and normal skin." (PMID 24744689, 2014). "Similar to CD8+ T cells, CD68+ macrophages were also significantly increased at the DEJ in DLE lesional skin versus both psoriasis lesional skin and normal skin." (PMID 24744689, 2014). "Correlation analysis showed that m6A levels in CD68+ cells, m6A modification of SLC15A3, and SLC15A3 mRNA levels were all positively correlated with psoriasis severity, as measured by the Psoriasis Area and Severity Index (PASI)." (PMID 40679079, 2025). "Taken together with clinical indicators in the dynamics of psoriasis treatment with PGZ, such as a decrease of PASI index and reduction of relapse rate up to 1-2 times per year, decreasing of CD68+ cells indicates inhibition of inflammation locally." (PMID 32411188, 2020). "We found that CD3+ T cells, CD8+ T cells, and CD68+ macrophages are significantly higher in the DEJ of DLE lesional skin versus normal and psoriasis lesional skin." (PMID 24744689, 2014). "CD20+ B cells and CD68+ macrophages were also elevated in the periadnexal areas of DLE lesional skin compared with normal and psoriasis lesional skin." (PMID 24744689, 2014). "In obese psoriasis patients, pioglitazone therapy did not significantly affect CD163+ (M2‐like) macrophage infiltration, indicating that its therapeutic impact is specifically targeted at CD68+ (M1‐like) pro‐inflammatory macrophages." (PMID 40539722, 2025).
Cirrhosis (16 papers, 2012 to 2023). A chronic disorder of the liver in which liver tissue becomes scarred and is partially replaced by regenerative nodules and fibrotic tissue resulting in loss of liver function. "When shown by group, the scRNA-seq data revealed a significant increase of Mono/Mac (clusters 2, 7, 8 and 17 which were CD14 and CD68 co-expressed) in the ACLF group compared with the cirrhosis group." (PMID 37380987, 2023). "High CD68 expression in clusters 2, 3, and 4 indicated resident liver macrophages, whereas low CD68 in clusters 0 and 1, mainly present in cirrhosis samples, indicated infiltrating macrophages." (PMID 37004869, 2023). "Macrophages are a key regulator of chronic inflammation and fibrosis in various disorders such as pericarditis, and hepatic cirrhosis and arteriosclerotic plaque, and in this study, among all cases, 63.5% involved CD68+ cells." (PMID 33882882, 2021). "Prevalence of hepatic CD68+AXL+ cells significantly decreased with cirrhosis progression: (healthy, 90.2%; Child-Pugh A, 76.1%; Child-Pugh B, 64.5%; and Child-Pugh C, 18.7%; all P < .05) and negatively correlated with Model for End-Stage Liver Disease and C-reactive protein (all P < .05)." (PMID 37004869, 2023). "Low numbers of CD68+ cells were found in the liver tissue sections of the control group indicating low macrophage activity in association with benign diseases; additionally, in D10 with diagnosed HCC and cirrhosis, the findings also indicated low macrophage activity in chronic diseases." (PMID 33918803, 2021). "Intra-hepatic CD68+ TAMs were increased 1.7 or 1.3-fold in HBV-HCC, compared to that from CHB or HBV-cirrhosis, respectively." (PMID 35347503, 2023). "In our current study, intra-hepatic CD68+ TAMs increased gradually with the order from CHB, HBV-cirrhosis to HBV-HCC patients." (PMID 35347503, 2023). "For patients with cirrhosis, IHC analyses illustrated significant intrahepatic infiltration of CD3+ T cells, Foxp3+ Tregs, IL-17+ T cells, CD20+ B cells, and CD68+ macrophages in the fibrotic areas." (PMID 35838051, 2022). "Consistently, we found that increased CD68 (human monocyte lineage/macrophages marker) and CXCL10 staining in livers of HBV-infection-induced hepatic cirrhosis patients compared with normal liver." (PMID 32641985, 2020). "In this study, we demonstrated that CD68+ TAMs and M2-polarized TAMs correlate with established clinicopathologic features of advanced de novo HCC in non-cirrhosis." (PMID 31170995, 2019). "Frequencies of CD68+, CD163+ M2-polarized TAMs and TILs were measured in de novo HCC tumours in non-cirrhosis (n = 58) using immunohistology and correlated to patients’ clinicopathological characteristics and survival rates." (PMID 31170995, 2019). "CD68 immunofluorescence staining of the liver samples further confirmed a significant increase of Mono/Mac infiltration in the ACLF liver compared with the HC and cirrhosis liver." (PMID 37380987, 2023). "From one patient with advanced cirrhosis (Child-Pugh C) who underwent transplantation, we investigated macrophages in mesenteric lymph nodes and observed the presence of CD68+AXL+ macrophages accumulating in the non-follicular regions." (PMID 37004869, 2023). "Intra-hepatic CD68+ TAMs were upregulated in HBV-HCC compared to that from CHB and HBV-cirrhosis." (PMID 35347503, 2023). "In human cirrhosis, COX-2+ cells showed to be CD68+ as well." (PMID 30212575, 2018). "Macrophages (CD68+) were prominently present in cirrhotic scars irrespective of the origin of cirrhosis." (PMID 25250030, 2014). "However, the present study applying high doses of caffeine (50 mg/kg) to cirrhotic rats showed that the pulmonary polymorphonuclear cells and CD68-positive staining macrophages were not attenuated, indicating a lack of therapeutic effect on pulmonary inflammation in cirrhosis." (PMID 30925782, 2019).
Cirrhosis (continued). "CD68 harbors, indeed, a highly sensitivity, with positivity up to 97% of cases, but specificity may be quite low, because CD68 is seen in 25% of HCC without cirrhosis and in 10% of HCC with cirrhosis." (PMID 26838800, 2015).
periodontitis (16 papers, 2020 to 2026). An acute or chronic inflammatory process that affects the tissues that surround and support the teeth. "Adaptive immune cells (plasma cells (CD138+), B cells (CD20+), and T cells (CD3+)) predominated in the periodontitis tissue (50%), whereas macrophages (CD68+) were poorly represented (1.3 ± 0.8%)." (PMID 41545496, 2026). "For four of the five IG score markers—CD138, CD20, CD68, and CD66b—the areas analyzed were significantly larger in patients with periodontitis than in healthy controls." (PMID 41545496, 2026). "CD68(+) macrophages were most abundant in the periodontitis group and least in the Melatonin group (p=0.00)." (PMID 41711848, 2026). "Subsequently, we investigated macrophage polarization and noted a significant decrease in M2 macrophages (CD68+CD163+) and an increase in M1 macrophages (CD68+CD86+) in periodontitis samples." (PMID 40277454, 2025). "In the inflamed tissue, a strong infiltration of IL-17-producing T cells was observed in the bottom region of chronic periodontitis lesions, while the Th17-inducing cytokine IL-23 was locally produced by CD68+ macrophages." (PMID 39253090, 2024). "Both M1 (CD68 + CD86+) and M2 (CD68 + CD206+) macrophages were increased in gingiva with periodontitis compared to healthy gingiva, which confirmed the results of IHC." (PMID 38689292, 2024). "IF results revealed Piezo1 located in macrophages (labeled by CD68) of periodontitis gingival tissues and in the LPS-stimulated RAW264." (PMID 37261355, 2023). "Histological staining showed obvious infiltration of inflammatory cells and CD68 positive macrophages were abundant in the periodontitis samples." (PMID 36991451, 2023). "MMP-12 expression found elevated in patients with chronic periodontitis with identification of CD68+ CD14+ CD64+ cells." (PMID 33892690, 2021). "Importantly, CD68-positive macrophages show cleaved caspase-3 in periodontitis and gingivitis patients." (PMID 32630157, 2020). "Another study found that IL-23 p19 was produced by CD68+ macrophages in experimental periodontitis, and in vitro generated CD68+ cells could be stimulated by Porphyromonas gingivalis-derived lipopolysaccharide to produce p19 mRNA suggesting that TLR signaling controls IL-23 production." (PMID 39253090, 2024). "Periodontitis saliva significantly reduced the percentages of CD14+, CD68+, and CD36+ cells versus healthy saliva, indicating a nudge of the monocytes and M0-type macrophages toward an inflammatory status but away from the M2 phenotype." (PMID 36207325, 2022). "The presence of macrophage markers CD14, CD86, CD68, and CD163 was examined in gingival biopsies from healthy individuals and periodontitis patients." (PMID 33513808, 2021). "To confirm the presence of macrophages, we also examined the expression of the macrophage markers CD14, CD68, CD86, and CD163 in gingival biopsies from periodontally healthy individuals and periodontitis patients." (PMID 33513808, 2021).
rheumatoid arthritis (16 papers, 2009 to 2025). A chronic, systemic autoimmune disorder characterized by inflammation in the synovial membranes and articular surfaces. "Characteristic histopathological manifestations of rheumatoid arthritis‐associated tenosynovitis encompass synovial hyperplasia with leukocytic infiltration, predominantly CD4+ T lymphocytes and CD68+ macrophages." (PMID 41409891, 2025). "In the treatment of rheumatoid arthritis, changes in the number of CD68+ macrophages are associated with clinical outcomes assessed by DAS28 and are considered a reliable biomarker for assessing the efficacy of rheumatoid arthritis treatments." (PMID 40836954, 2025). "It is known to be distributed in hair follicles and keratinocytes, and a recent report indicated that PADI3 was strongly stained in macrophages (CD68-positive cells) in rheumatoid nodules and synovial tissue." (PMID 31532791, 2019). "CD68/CD163+ synoviocytes were preferentially located in the vicinity of the synovial lining layer of rheumatoid arthritis patients while they were randomly distributed in PVNS." (PMID 21899757, 2011). "Immunohistochemical staining of rheumatoid nodules has shown positive staining of epithelioid cells for HLA-DR, CD68, lysozyme, MMP-2, MMP-3, MMP-9 and Ki67." (PMID 19604347, 2009). "The change in number of CD68-positive sublining macrophages in serial synovial biopsies has been successfully used to discriminate on the group level between effective and ineffective treatment during early drug development in rheumatoid arthritis (RA) patients." (PMID 25166859, 2014). "It has already been established in rheumatoid arthritis (RA) that the mean change in DAS28 correlates with the mean change in synovial sublining CD68 expression across several RA patient cohorts receiving different therapeutic agents." (PMID 21272347, 2011). "In this study, we examined the expression of AIF-1 isoforms on the level of mRNA, and we compared the percentage of AIF-1-positive white blood cells (WBCs) in blood and AIF-1/CD68 cells in the synovial membranes in patients with rheumatoid arthritis (RA) and osteoarthritis (OA)." (PMID 32708725, 2020). "Synovial tissue specimens (normal synovium, n=15; orthopedic arthropathies, n=6; osteoarthritis, n=26; early undifferentiated arthritis, n=10; rheumatoid arthritis, n=26; chronic septic arthritis, n=11) were stained for CD15, CD68, CD3, CD20, and CD38." (PMID 23951325, 2013). "However, elevated expression of miR-223 in CD68+ macrophages, CD14+ monocytes, and CD4+ T cells from synovium of rheumatoid arthritis (RA) patients was reported." (PMID 34222229, 2021).
amyloid (15 papers, 2013 to 2025). "These genes, Thy1, Gfap, Tyrobp, Ctsd, Cst7, C1qb, Lyz2, Ctss, Trem2, Mpeg1, Hexb, Cd68, C1qb, C1qa, Ctsz, Grn, Laptm5, B2m, C1qc, Hexa, and Serpina3n, were increased in the 7-month-old 5XFAD model in the cortex and associated with amyloid plaque image patterns." (PMID 38036733, 2023). "Besides CD68, the amyloid plaque-associated macrophage population in the APP-PS1 mice sporadically co-localized with MHCII further supporting the macrophage identity of these cells and indicating that these cells are probably involved in antigen presentation." (PMID 30241479, 2018). "Microglia from platelet-depleted mice showed similar CD68+ phagolysosome volume compared with control mice but lower amounts of internalized amyloid plaque content and increased numbers of plaque-associated Iba1+ microglia." (PMID 36734880, 2023). "TREM2 was correlated with Iba1, TMEM119, and CD68, consistent with TREM2 upregulation in specific phenotypes of disease or amyloid-associated microglia." (PMID 33178186, 2020). "In our study, APP/Arg1 insufficient mice showed increased CD68 expression in HPC and ECX compared to APP/Arg1 sufficient mice and nTg/Arg1 insufficient mice, suggesting that amyloidosis and Arg1 deficiency promoted CD68 expression." (PMID 33519806, 2020). "To validate the neuroinflammatory potential of Notch1 and amyloid plaques, we performed the triple immunolabeling with the activated microglia marker, CD68 (a–a”)." (PMID 27364742, 2016). "Next, we explored whether other microglial markers, such as the microglia-associated triggering receptor expressed on myeloid cells (TREM2) and CD68, that may be altered in the presence of amyloid pathology, were affected by DHA treatment." (PMID 36678710, 2022). "Despite increased microglia activation measured by IBA1 and CD68, these data strongly suggest that several components of the Ragulator-Rag complex are up-regulated during amyloidosis and reduced with Arg1 insufficiency, indicating a potential deficit in microglial digestion machinery." (PMID 33519806, 2020). "Sham-irradiated APP/PS1 females had significantly higher percent ROI of CD68 immunoreactivity than sham-irradiated APP/PS1 males (p = 0.0008), likely due to higher amyloid plaque load." (PMID 34948098, 2021). "Ordinal logistic and multiple linear regression analysis of amyloid and tau pathology with CD68 did not exhibit any significant relationships." (PMID 32076055, 2020). "This might partly reflect the response of both CD68 and clustered GFAP signal to amyloid plaque buildup, perhaps pointing towards coordination of microglial and astrocytic phagocytosis, as reactive astrocytes are also capable of internalizing Aβ." (PMID 32197653, 2020). "Furthermore, microglial levels of CD68 were unchanged between the 3xTg groups in CA1, a region that does not display amyloid pathology in these mice." (PMID 35787714, 2022).
lupus nephritis (15 papers, 2013 to 2026). Glomerulonephritis in the context of systemic lupus erythematosus. "Elevated levels of CD68 expression have been reported to be associated with lupus nephritis and diabetic nephropathy." (PMID 40529491, 2025). "In an interesting observation, they found that glomeruli with ≥7 CD-68 positive macrophages had a good concordance for endocapillary hypercellularity in lupus nephritis." (PMID 38612574, 2024). "They found that CD68-positive-macrophages were higher in the patients with active class IV lupus nephritis in comparison with class II and class V lupus nephritis." (PMID 38612574, 2024). "CD68-positive macrophages were utilized as a surrogate for endocapillary hypercellularity of lupus nephritis in a multi-centric study performed in the Netherlands and United Kingdom." (PMID 38612574, 2024). "The number of these cells in MI patients from the studied group was comparable to the number of CD68+ cells in the kidneys of patients with a reduced glomerular filtration rate and the presence of lupus nephritis." (PMID 37509483, 2023). "In lupus nephritis tissue, infiltration of CD68+ cells expressing NLRP3, a molecule upregulated in Mo stimulated with snRNP IC, was associated with treatment outcomes, supporting an important role for MPs in lupus nephritis." (PMID 41648138, 2026). "The relevance of macrophages for the pathogenesis of lupus nephritis has been shown in several studies, e.g., there is correlation between the numbers of infiltrating CD68+ macrophages and monocytes and clinical outcome parameters, such as proteinuria, in human lupus nephritis." (PMID 27091114, 2016). "Finally, CD47+ CD68+ macrophages were present in lupus nephritis." (PMID 34068752, 2021). "Interestingly, intra-glomerular CD68+ macrophages in class IV lupus nephritis patients with high disease activity expressed pSHP-1S591 suggesting that SHP-1 status may contribute to disease pathogenesis by failing to downregulate FcγRIIA activity." (PMID 28811476, 2017). "Using immunohistochemical analysis we analyzed renal biopsies from 68 patients with lupus nephritis (ISN/RPS classes II–V) for infiltration with M1-like (iNOS+/CD68+), M2a-like (CD206+/CD68+), M2c-like macrophages (CD163+/CD68+), and FoxP3+ regulatory T-cells." (PMID 27091114, 2016). "Our previous study mentioned that the inhibition of miR-150 in lupus nephritis can reduce the infiltration of total macrophages by just examining CD68, a total macrophage biomarker; we had not performed subsets of macrophages." (PMID 35990680, 2022). "Immunohistochemical staining showed that vehicle- or TAC-treated lupus nephritis kidneys had increased levels of CD68+ cells and F4/80+ mononuclear macrophages, whereas the levels of these cells were profoundly decreased in the glomerulus of HGC-TAC-treated lupus nephritis mice." (PMID 33865397, 2021). "Finally, we showed that high serum levels of soluble E-selectin protein (sE-selectin) ameliorates the progression of lupus nephritis and vasculitis by suppressing infiltration of both CD8+ T cells and CD68+ macrophages in transgenic (Tg) MRL/lpr mice expressing a sE-selectin gene." (PMID 25400916, 2013).